ZBTB37 (zinc finger and BTB domain containing 37)
Description:
May be involved in transcriptional regulation.
Synonyms: MGC2629; ZNF908; D430004I08Rik
Tractability: PROTAC: ubiquitination databases record sites on it.
Gene: Protein-coding gene on chromosome 1 (173,868,082 to 173,903,547, forward strand). Ensembl gene ENSG00000185278.
Subcellular location: Nucleus
Subcellular location (Human Protein Atlas): Nucleoli fibrillar center; Nucleoplasm; Cytosol
Gene Ontology:
Molecular function: sequence-specific double-stranded DNA binding; DNA-binding transcription factor activity, RNA polymerase II-specific; DNA-binding transcription repressor activity, RNA polymerase II-specific; RNA polymerase II cis-regulatory region sequence-specific DNA binding
Biological process: negative regulation of transcription by RNA polymerase II; regulation of cytokine production; regulation of immune system process
Cellular component: chromatin; nucleoplasm; nucleus
Genetic constraint (gnomAD): Loss-of-function variants: 15 observed, 39.61 expected, observed/expected ratio (o/e) 0.38, 90% interval 0.25 to 0.58. The upper end of that interval is the gene's LOEUF score, 0.58, which puts it in group 2 of 6, group 1 being the genes least tolerant of losing a copy. Missense variants: 514 observed, 673.46 expected, observed/expected ratio (o/e) 0.76, 90% interval 0.71 to 0.82. Synonymous variants: 231 observed, 232.67 expected, observed/expected ratio (o/e) 0.99, 90% interval 0.89 to 1.11.
Homologues: Orthologues: chimpanzee ZBTB37 (100% identical), macaque ZBTB37 (99% identical), dog ZBTB37 (98% identical), pig ZBTB37 (98% identical), rabbit ZBTB37 (98% identical), guinea pig ZBTB37 (95% identical), rat Zbtb37 (95% identical), mouse Zbtb37 (95% identical), tropical clawed frog zbtb37 (85% identical), zebrafish zbtb37 (71% identical). Paralogues in human: ZBTB34 (46% identical), ZNF84 (19% identical), ZNF107 (19% identical), ZNF160 (19% identical), ZNF420 (18% identical), ZNF91 (18% identical), ZNF473 (18% identical), ZNF594 (18% identical), ZNF99 (17% identical), ZNF184 (17% identical), ZNF208 (17% identical), ZNF729 (16% identical), and 24 more.
Diseases named in the same sentence as ZBTB37 in open-access papers:
ZBTB37 is named in the same sentence as 2 diseases in open-access papers, as found by Europe PMC text mining. Sharing a sentence is not in itself a finding about the gene and the disease.
ZBTB37 shares sentences with these, for which no sentence is quoted: breast carcinoma (1 paper); type 2 diabetes (1).